INSM1 (INSM transcriptional repressor 1)
Description:
Sequence-specific DNA-binding transcriptional regulator that plays a key role in neurogenesis and neuroendocrine cell differentiation during embryonic and/or fetal development. Binds to the consensus sequence 5'-[TG][TC][TC][TT][GA]GGG[CG]A-3' in target promoters. Acts as a transcriptional repressor of NEUROD1 and INS expression via its interaction with cyclin CCND1 in a cell cycle-independent manner. Negatively regulates skeletal muscle-specific gene expression in endocrine cells of the pituitary by inhibiting the Notch signaling pathway. Represses target gene transcription by recruiting chromatin-modifying factors, such as HDAC1, HDAC2, HDAC3, KDM1A and RCOR1 histone deacetylases. Binds to its own promoter, suggesting autoregulation as a self-control feedback mechanism. Competes with histone H3 for the same binding site on the histone demethylase complex formed by KDM1A and RCOR1, and thereby inhibits demethylation of histone H3 at 'Lys-4'. Promotes the generation and expansion of neuronal basal progenitor cells in the developing neocortex. Involved in the differentiation of endocrine cells of the developing anterior pituitary gland, of the pancreas and intestine, and of sympatho-adrenal cells in the peripheral nervous system. Promotes cell cycle signaling arrest and inhibition of cellular proliferation.
Synonyms: IA1; IA-1
Tractability: Small molecule: a structure with a bound ligand is known.
Gene: Protein-coding gene on chromosome 20 (20,368,104 to 20,370,949, forward strand). Ensembl gene ENSG00000173404.
Subcellular location: Nucleus
Pathways (Reactome):
Developmental Biology: Regulation of gene expression in endocrine-committed (NEUROG3+) progenitor cells
Gene Ontology:
Molecular function: chromatin DNA binding; cyclin binding; DNA-binding transcription factor activity; DNA-binding transcription repressor activity, RNA polymerase II-specific; histone deacetylase binding; molecular adaptor activity; RNA polymerase II cis-regulatory region sequence-specific DNA binding
Biological process: negative regulation of cell population proliferation; negative regulation of protein phosphorylation; negative regulation of transcription by RNA polymerase II; regulation of cell cycle; regulation of protein-containing complex assembly; transdifferentiation; adrenal chromaffin cell differentiation; neuron differentiation; noradrenergic neuron development; norepinephrine biosynthetic process; pancreatic A cell differentiation; positive regulation of cell differentiation; positive regulation of neural precursor cell proliferation; regulation of cell cycle process; regulation of gene expression; sympathetic ganglion development; type B pancreatic cell differentiation; cell differentiation; regulation of cell population proliferation
Cellular component: transcription repressor complex; nucleoplasm; nucleus
Genetic constraint (gnomAD): Loss-of-function variants: 14 observed, 9.24 expected, observed/expected ratio (o/e) 1.51, 90% interval 0.97 to 1.93. That is too few expected variants to judge how well the gene tolerates losing a copy. Missense variants: 744 observed, 441.89 expected, observed/expected ratio (o/e) 1.68, 90% interval 1.59 to 1.79. Synonymous variants: 411 observed, 238.7 expected, observed/expected ratio (o/e) 1.72, 90% interval 1.59 to 1.87.
Homologues: Orthologues: macaque INSM1 (97% identical), pig INSM1 (96% identical), rat Insm1 (94% identical), mouse Insm1 (93% identical), tropical clawed frog insm1 (54% identical), zebrafish insm1b (52% identical), zebrafish insm1a (49% identical), Drosophila melanogaster nerfin-1 (23% identical), Caenorhabditis elegans egl-46 (18% identical). Paralogues in human: INSM2 (41% identical).
Diseases named in the same sentence as INSM1 in open-access papers:
INSM1 is named in the same sentence as 110 diseases in open-access papers, as found by Europe PMC text mining. Sharing a sentence is not in itself a finding about the gene and the disease. The quoted sentences say what the papers report.
neuroendocrine tumors (43 papers, 2011 to 2026). "INSM1 has since been applied as a diagnostic marker for neuroendocrine neoplasms in various organs, including the lung, pancreas, and prostate." (PMID 40805240, 2025). "INSM1 is a critical regulator of neuroendocrine cell development and is a diagnostic immunohistochemical marker for neuroendocrine tumors." (PMID 41392987, 2025). "Insulinoma-associated protein 1 (INSM1) is a nuclear transcription factor, expressed in neuroendocrine neoplasms (NENs)." (PMID 38482526, 2024). "Insulinoma-associated protein 1 (INSM1) has been identified as a nuclear marker of neuroendocrine tumors." (PMID 36531655, 2022). "INSM1 protein expression has been mostly investigated as a diagnostic immunohistochemical marker for neuroendocrine neoplasms in different organs and settings." (PMID 35608806, 2022). "Recent studies have identified insulinoma-associated protein 1 (INSM1) as a sensitive and specific neuroendocrine marker for the diagnosis of all neuroendocrine tumors including SCLC." (PMID 33202998, 2020). "If alleles of Insm1 are indeed responsible for the two tumor subtypes, then Insm1 should be capable of blocking metastasis and dedifferentiation in neuroendocrine tumor cell lines." (PMID 30796198, 2019). "Insulinoma associated-1 (IA-1/INSM1) gene is exclusively expressed during early embryonic development, but has been found to be re-expressed at high levels in neuroendocrine tumors including neuroblastoma." (PMID 26456864, 2015). "Overall, the efficacy of insulinoma-associated protein 1 (INSM1) as an immunohistochemical marker for neuroendocrine neoplasms has been supported by various clinical studies demonstrating its high sensitivity and even higher specificity for detecting NETs of various sites." (PMID 34943408, 2021). "The second marker INSM1, a zinc finger transcription factor is implicated in the differentiation of endocrine cells in the pituitary and other tissues 51, and its expression is significantly increased in multiple neuroendocrine neoplasms." (PMID 33391466, 2021). "Insulinoma-associated protein 1 (INSM1) has been considered as a novel immunostaining marker for neuroendocrine tumors (NETs) and is hypothesized to be more reliable than first-generation NET biomarkers, such as CGA (chromogranin A), SYP (synaptophysin), and CD56 (neural cell adhesion molecule)." (PMID 36531655, 2022). "Furthermore, insulinoma-associated-1 (INSM1), which encodes a zinc-finger transcription factor, has recently emerged as a specific neuroendocrine transcription factor and a sensitive biomarker for neuroendocrine tumors." (PMID 33170304, 2021). "INSM1 is a novel immunostain for neuroendocrine tumors, specifically SCNCs of the genitourinary tract." (PMID 41333490, 2025). "ASCL1 and INSM1 serve as markers for neuroendocrine tumours, such as for small cell lung carcinoma (SCLC)." (PMID 40257984, 2025). "Instead, the guidelines recommend CgA, SYP, and INSM1 expressions as immunohistochemical markers for neuroendocrine neoplasms of the head and neck region." (PMID 39937015, 2025). "We further annotated tumor cells using four markers closely associated with neuroendocrine tumors: ASCL1, NCAM1, INSM1, and GRP." (PMID 40213972, 2025). "TRPS1 and INSM1 are sensitive markers for predicted breast and neuroendocrine neoplasms, respectively." (PMID 38041048, 2023). "Nonetheless, TRPS1 and INSM1 were reliable markers of predicted breast carcinoma (75.0%) and neuroendocrine tumors (83.3%), respectively." (PMID 38041048, 2023). "Neuroendocrine neoplasms are diagnosed by immunostaining, such as specific stains for synaptophysin, chromogranin A and INSM1." (PMID 37027114, 2023). "The sensitivity of INSM1 was found to be 80.0%, thus indicating its role as a valuable marker of neuroendocrine differentiation in both primary and metastatic neuroendocrine neoplasms." (PMID 38041048, 2023).
neuroendocrine tumors (continued). "We discovered that N-Myc oncoprotein binds and activates INSM1, a zinc-finger transcription factor of neuroendocrine tumors." (PMID 37627018, 2023). "INSM1 is a reliable diagnosis marker in neuroendocrine tumors that has attracted much attention in recent years." (PMID 36531655, 2022). "Although its mRNA levels are significantly reduced in healthy adult tissues, INSM1 is expressed in various neuroendocrine tumours such as insulinomas, pituitary adenomas and medullary thyroid carcinomas, and it is also a specific marker for SCLC." (PMID 36362289, 2022). "Although INSM1 appears to be a subtle and specific biomarker for neuroendocrine tumors, its expression in mesenchymal tumors and its clinicopathological significance are still unclear." (PMID 36531655, 2022). "INSM1 was slightly less sensitive (80.9%) for detection of gastroenteric neuroendocrine neoplasms than that of SYP (99.1%), CGA (88.6%), and CD56 (95.3%) while it was more specific (95.7% vs 86.0%, 87.3%, and 86.0%, respectively)." (PMID 34943408, 2021). "INSM1 marker expression has been suggested to be prognostic in high-grade neuroendocrine neoplasms, but if INSM1 expression has a prognostic impact in ADC or SqCC remains to be investigated." (PMID 33933015, 2021). "On the other hand, INSM1 nuclear staining was found to be easier to interpret, with a superior 99% overall sensitivity across different neuroendocrine tumors of the head and neck and, specifically, with 95.8% sensitivity for PD NECs such as SC-NEC." (PMID 34638312, 2021). "INSM1 is particularly expressed in neuroendocrine tumors, including pituitary tumors, neuroblastoma, and retinoblastoma, and INSM1 is considered as a neuroendocrine marker of high specificity." (PMID 32670859, 2020). "Coupled with the genetic linkage experiments from RT2 AB6F2 mice, the cell line data strongly suggest that allelic differences in Insm1 between the A/J and B6 mouse lines lead to different types of neuroendocrine tumors in RT2 mice." (PMID 30796198, 2019). "Insulinoma associated-1 (INSM1) gene is expressed exclusively in early embryonic neuroendocrine tissues, but has been found highly re-activated in most of the neuroendocrine tumors including small cell lung carcinoma." (PMID 27072116, 2016). "Insm1 was originally identified as highly expressed in neuroendocrine tumors, but during normal development it is transiently expressed throughout the embryonic and adult developing nervous system." (PMID 21284846, 2011). "When dealing with limited diagnostic tissue, in the appropriate clinicopathologic context, INSM1 could be essential as a stand-alone marker for excluding a neuroendocrine neoplasm." (PMID 40909976, 2025). "Among morphologically non‐neuroendocrine tumours, the number of cases showing positivity for at least two neuroendocrine markers was the same for synaptophysin/chromogranin A compared to synaptophysin/INSM1." (PMID 39526928, 2025). "Although solid medullary neoplasms of the pancreas were raised as differential diagnosis, neuroendocrine neoplasms were excluded based on the negative immunohistochemical staining for synaptophysin, chromogranin A, and insulinoma-associated protein 1 (INSM1)." (PMID 40236650, 2025). "First, the lesion was initially diagnosed on EUS-FNA cytology as a well-differentiated neuroendocrine tumor (NET), illustrating a recognized diagnostic pitfall when SPNs show focal expression of neuroendocrine markers (e.g., synaptophysin, INSM1) and when material is limited." (PMID 41261629, 2025). "Although INSM1 appears to be a subtle and specific biomarker for neuroendocrine tumor, its expression and clinicopathological significance in mesenchymal tumors remain unclear." (PMID 36531655, 2022).
neuroendocrine tumors (continued). "INSM1 was positive in 82.9% of well-differentiated neuroendocrine tumors (58/70), 85.0% of poorly differentiated neuroendocrine carcinomas (17/20), 72.7% of low-grade goblet cell adenocarcinomas (8/11) (grade 1), and 66.7% of high-grade goblet cell adenocarcinomas (6/9) (grade 2/3)." (PMID 34943408, 2021). "SCLC shows a variable expression of neuroendocrine differentiation markers such as neural cell adhesion molecule (NCAM/CD56), chromogranin, synaptophysin, and insulinoma-associated protein 1 (INSM1), and usually presents lower protein levels than low-to-intermediate grade neuroendocrine tumors." (PMID 33669241, 2021). "Our results revealed that INSM1 is also a highly sensitive diagnostic marker for tumor invasion in non-functioning pituitary neuroendocrine tumors, with strong nuclear staining and homogenous expression pattern." (PMID 33391466, 2021). "INSM1 is mainly expressed in neuroendocrine tissues at some development stages, and especially expressed at a high level in central nervous tissues, pancreatic islets, and neuroendocrine tumors." (PMID 32670859, 2020). "Since INSM1 is also highly expressed in tumors of neuroendocrine origin, its promoter could serve as a tumor-specific target for gene therapy for neuroendocrine tumors." (PMID 21609490, 2011). "Insm1 is also highly expressed in medulloblastomas and other neuroendocrine tumors." (PMID 21284846, 2011). "Reactivation of INSM1 has been observed in insulinoma, pheochromocytoma, pituitary tumor, medullary carcinoma of the thyroid, medulloblastoma, neuroblastoma, retinoblastoma, small-cell lung cancer, and neuroendocrine tumors of the head and neck/skin/prostate/female genital tract." (PMID 36531655, 2022). "However, the INSM1 gene is known to be reactivated in neuroendocrine tumors." (PMID 21609490, 2011). "Markers such as INSM1 and CD117, along with traditional neuroendocrine markers, assist in diagnosing lung neuroendocrine tumors, particularly in identifying small cell lung carcinoma." (PMID 40486880, 2025). "SOX2 and INSM1 are frequently expressed in MCC and other neuroendocrine tumors and are regarded as markers for a neuroendocrine phenotype." (PMID 34667274, 2022). "As non-neuroendocrine tumors seldom express these antigens, the specificity of ISL1, INSM1 and SECG make them welcome additions to clinical practice." (PMID 34571751, 2021). "The diagnostic arsenal has since expanded, with ISL LIM homeobox 1 (ISL1), INSM transcriptional repressor 1 (INSM1), and secretagogin (SECG) to name a few novel markers exhibiting high sensitivity and specificity for neuroendocrine neoplasms (NENs)." (PMID 32813226, 2020). "Eight genes (CHGA, CPE, ENO2, INSM1, PTPRN2, SERPINA10, and SLC18A1/2) that have been previously identified as markers of neuroendocrine tumors were confirmed in this study to be altered." (PMID 21853033, 2011). "Laparoscopic appendectomy confirmed residual SSL with HO and an adjacent 4.5-mm grade-1 neuroendocrine tumor (INSM1+, Ki-67 <3%) with negative margins." (PMID 41450897, 2026). "All cases showed a lack of expression of INSM1, a more recent marker of neuroendocrine differentiation with reportedly superior performance in the diagnosis of thoracic neuroendocrine tumors." (PMID 40909976, 2025). "Additionally, LCA (-) excludes lymphoid tumors, while CD56 (-), CgA (-), INSM1 (-), and Syn (-) eliminate the possibility of neuroendocrine tumors." (PMID 39723371, 2024). "Additionally, among the predicted neuroendocrine neoplasms, seven of 10 cases (70.0%) expressed the classical markers of neuroendocrine cell differentiation (Syn, CgA, and CD56), and four of five cases (80.0%) were INSM1 positive." (PMID 38041048, 2023). "Interestingly, Insm1 is not the only allelic difference between the B6 and A/J lineages that affects neuroendocrine tumors." (PMID 30796198, 2019).
neuroendocrine tumors (continued). "However, the updated WHO classification discourages the use of CD56 due to its non-specificity for neuroendocrine neoplasms (NENs) and instead advocates for CgA, SYP, and insulinoma-associated protein 1 (INSM1) as novel markers of neuroendocrine differentiation in the head and neck region." (PMID 39937015, 2025). "However, for setting up SOX11, INSM1, and MEOX2 assays, tissues with the strongest expression were chosen, given the lack of weak expressing tissues and general need to identify strong expressing cells of mantle cell lymphoma (SOX11), neuroendocrine tumours (INSM1), and endothelium (MEOX2)." (PMID 37568909, 2023).